LINC01852 (long independently transcribed non-coding RNA 1852)
Synonyms: ENST00000434223
Gene: Long non-coding RNA gene on chromosome 15 (38,068,812 to 38,073,096, reverse strand). Ensembl gene ENSG00000236914.
Diseases named in the same sentence as LINC01852 in open-access papers:
LINC01852 is named in the same sentence as 3 diseases in open-access papers, as found by Europe PMC text mining. Sharing a sentence is not in itself a finding about the gene and the disease. The quoted sentences say what the papers report.
cancer (2 papers, 2022 to 2024). A tumor composed of atypical neoplastic, often pleomorphic cells that invade other tissues. "We revealed that LINC01852 is downregulated in CRC and that its overexpression inhibits cancer cell growth and chemoresistance." (PMID 38263157, 2024). "AC129507.1, AC068580.3, and LIMD1-AS1 were thought to play important roles in different cancers, while AC005253.1, AC127502.2, and LINC01852 were identified for the first time." (PMID 36248980, 2022). "This study demonstrated that LINC01852 acts as a molecular scaffold to facilitate the interaction between SRSF5 and TRIM72, promoting TRIM72-mediated degradation of SRSF5, and these findings reveal a novel lncRNA-based mechanism that regulates SRSF5 expression and function in cancer cells." (PMID 38263157, 2024).
tumor (1 paper, 2024). "To identify the potential mechanism mediating the tumor-inhibitory effects of LINC01852, we performed RNA pull-down assays to isolate LINC01852-associated proteins from CRC cells." (PMID 38263157, 2024). "First, we found that overexpression of SRSF5 and PKM2 partially reversed the tumor suppressive effect of LINC01852." (PMID 38263157, 2024). "The results indicated that LINC01852 and SRSF5 potentially regulate multiple tumor-related signaling pathways." (PMID 38263157, 2024). "Mechanistically, LINC01852 functioned as a molecular scaffold to enhance the interaction of TRIM72 with SRSF5 and facilitate TRIM72-mediated degradation of SRSF5, thus inhibiting aerobic glycolysis, tumor growth and chemoresistance." (PMID 38263157, 2024). "Mechanistically, LINC01852 binds serine/arginine rich splicing factor 5 (SRSF5) and promotes its degradation and suppresses SRSF5-mediated alternative splicing of PKM2, thereby inhibiting aerobic glycolysis, tumor growth and chemoresistance." (PMID 38263157, 2024).
LINC01852 also shares sentences with these, for which no sentence is quoted: colorectal cancer (1 paper).